TPO (thyroid peroxidase)
Diseases named in the same sentence as TPO in open-access papers (continued):
Sharing a sentence is not in itself a finding about the gene and the disease.
hypothyroidism (continued). "Hypothyroidism with increased TSH and anti-TPO levels may have a negative impact on obstetric history, resulting in the loss of an early pregnancy." (PMID 34667679, 2021). "However, we cannot conclusively state that these participants were anti-TPO negative before COVID-19, and AAB induction is a consequence of SARS-CoV-2 infection since anti-TPO positivity can occur without hypothyroidism, as observed in 16 out of 19 participants in the long COVID group." (PMID 39450181, 2024). "How does subclinical hypothyroidism, defined in infertile women during preconception by thyroid-stimulating hormone (TSH) >2.5 or >4.5 mIU/l, with or without thyroid peroxidase antibodies (anti-TPO) >100 IU/ml, impact thyroid hormone levels during pregnancy and after birth?" (PMID 37869413, 2023).
autoimmune thyroid disease (371 papers, 2004 to 2026). Inflammatory disease of the thyroid gland due to autoimmune responses leading to lymphocytic infiltration of the gland. "Our results reveal that anti-TPO positivity, a hallmark of autoimmune thyroiditis, is associated with elevated hsCRP levels and more pronounced clinical symptoms in SCH+ patients compared to SCH- patients and controls." (PMID 39902025, 2025). "It was assessed that the higher the adherence to the Mediterranean diet, the lower the anti-TPO and the greater protection against the risk of developing thyroid autoimmunity." (PMID 40290095, 2025). "A systematic review found that vitamin D supplementation was associated with reduced thyroid peroxidase antibody levels, which are critical markers of autoimmune thyroid disease." (PMID 40822954, 2025). "Among these, autoimmune thyroid disease—especially the presence of elevated anti-TPO antibodies—has been recurrently associated with RRV." (PMID 40869987, 2025). "Several authors have reported lower AMH levels and AFC values in anti-TPO-positive women, suggesting a potential pathogenic role for thyroid autoimmunity (TAİ) in ovarian aging." (PMID 41303060, 2025). "Selenium supplementation in patients with autoimmune thyroiditis (e.g., Hashimoto’s disease) has been associated with reductions in anti-thyroid peroxidase (TPO) antibody titers and improvements in antibody levels over 6–12 months." (PMID 41471071, 2025). "Considering the single increase in the titer of antibodies to thyroid peroxidase, a differential diagnosis was conducted for steroid-responsive encephalopathy associated with autoimmune thyroiditis (SREAT), also known as Hashimoto's encephalopathy." (PMID 39949448, 2025). "Among many other biomarkers, one of the key indicators of autoimmune activity is the presence of thyroid peroxidase antibodies (anti-TPO), which are associated with thyroid diseases such as autoimmune thyroid disease." (PMID 40075855, 2025). "A previous meta-analysis demonstrated an elevated breast cancer risk among patients with autoimmune thyroiditis, particularly in those with anti-thyroid peroxidase (anti-TPO) and anti-thyroglobulin (anti-TG) antibodies." (PMID 40567613, 2025). "Iron deficiency, by impairing TPO and deiodinase activity, has also been linked to a higher risk and greater activity of autoimmune thyroid diseases." (PMID 41157208, 2025). "Anti-TPO antibodies, markers of autoimmune thyroiditis, have been linked to altered glucose metabolism in some studies, though results remain inconsistent." (PMID 40600010, 2025). "This study aimed to evaluate the association between the exon 11 SNP of the TPO gene—rs1126797—and the development and clinical course of autoimmune thyroiditis in a Caucasian Polish population." (PMID 40650076, 2025). "Anti-TPO antibody levels were also positively correlated with hsCRP levels (r = 0.58, P < 0.001), indicating a strong association between thyroid autoimmunity and systemic inflammation." (PMID 39902025, 2025). "TPOAb is an autoantibody against the enzyme thyroid peroxidase and is commonly associated with autoimmune thyroid diseases such as Hashimoto thyroiditis." (PMID 39864955, 2025). "Background/Objectives: Thyroid autoimmunity, particularly anti-thyroid peroxidase antibodies (anti-TPO), has been implicated in reduced fertility and diminished ovarian reserve." (PMID 41303060, 2025). "It has been reported that the expression of the TPO gene (encoding thyroid peroxidase, a key factor of the autoimmune thyroid disease pathway) is up-regulated in Bashang long-tail chicken (BS) and Rhode Island red chickens (RIR) in cold environments." (PMID 38166615, 2024). "A hallmark biochemical feature of autoimmune thyroid diseases is the presence of thyroid autoantibodies in the serum, which target two major thyroid antigens: thyroid peroxidase (TPO) and thyroglobulin (Tg)." (PMID 39767195, 2024).
autoimmune thyroid disease (continued). "Hypothyroidism in women of reproductive age is predominantly caused by autoimmune mechanisms, and thyroid peroxidase autoantibodies (TPO-Ab) as well as thyroglobulin autoantibodies (Tg-Ab) are the key markers of underlying thyroid autoimmunity." (PMID 39090762, 2024). "Since thyroid autoimmunity is the leading cause of thyroid disease in women of reproductive age in developed countries, future studies should consider the role of TPO-Ab positivity and its influence on offspring metabolic health." (PMID 39090558, 2024). "SREAT is linked to autoimmune thyroiditis, including Hashimoto's thyroiditis, and is frequently associated with positive serum anti-thyroid antibodies, including anti-thyroid peroxidase (anti-TPO) and anti-thyroglobulin antibodies." (PMID 39473654, 2024). "After extensive workup, he was found to have anti-thyroid peroxidase antibodies and diagnosed with steroid-responsive encephalopathy associated with autoimmune thyroiditis (SREAT)." (PMID 37303426, 2023). "Aleksander et.al suggested that TPO rs11675434 polymorphism was related with autoimmune thyroid disease among Polish Caucasian population." (PMID 36737753, 2023). "To detect a possible association between autoimmune thyroiditis and HS, we also measured thyroid antibodies TRAb, TPO-Ab and Tg-AB." (PMID 38068542, 2023). "The anti-thyroid peroxidase antibody (anti-TG Ab) was the first antibody reported to be associated with autoimmune thyroid disease (AITD)." (PMID 38192953, 2023). "The abundance of 18 types of gut bacteria (for example Helicobacter pylori, Yersinia enterocolitica, etc.), was demonstrated to be linked with infection-associated autoimmune thyroiditis and positively correlated with anti-TPO and anti-TG." (PMID 37763034, 2023). "Anti-TPO antibodies are considered a sensitive way to detect early subclinical forms of autoimmune thyroiditis and, at the same time, identify patients at increased risk of developing autoimmune thyroid pathologies." (PMID 36556267, 2022). "Although the serologic markers such as anti-TPO and anti-Tg are frequently used in the diagnosis of autoimmune thyroid disease, their fluctuations are indeed associated with HT but are not a very sensitive predictor of HT4." (PMID 35768466, 2022). "TPO antibodies indicate an increased risk of the presence or future presence of autoimmune thyroid diseases, such as Graves’ disease and Hashimoto’s disease." (PMID 33542178, 2021). "To evaluate the potential contribution of autoimmune thyroiditis to the risk of developing AD early, we evaluated TPO antibody levels; these were available for only approximately 41% (96/232) of the entire cohort." (PMID 34573243, 2021). "TPO antibody detection frequency is ∼13% in healthy individuals (who are at risk for developing autoimmune thyroiditis), is more common among women and prevalence increases with age (27% of women >60 years old)." (PMID 34061124, 2021). "Anti-thyroid peroxidase antibodies (TPO-Ab) are auto-antibodies responsible for autoimmune thyroid disease and have been associated with subclinical atherosclerosis." (PMID 34945778, 2021). "It is agreed that high TG Ab or TPO Ab levels were considered to be at risk of thyroid cancer and thyroid autoimmunity." (PMID 31840740, 2020). "Anti-thyroid peroxidase antibody (TPO-Ab) causes autoimmune thyroid disease by bolstering thyroid inflammation." (PMID 33007021, 2020). "By bolstering thyroid inflammation, anti-peroxidase antibody (TPO-Ab) causes autoimmune thyroiditis, which is one of the most common causes of SCH." (PMID 33007021, 2020). "Anti-thyroid peroxidase antibody (TPO-Ab) has been shown to cause autoimmune thyroiditis by inducing a deleterious influence on thyroid hormone synthesis." (PMID 32085700, 2020). "TPO is not only a key enzyme involved in thyroid hormone synthesis but also an important antigen responsible for causing autoimmune thyroid disease." (PMID 32461982, 2020).
autoimmune thyroid disease (continued). "Infection with T. gondii has been associated with autoimmune thyroid diseases, an elevation of autoantibodies to thyroid peroxidase, and a mild increase of thyroid hormone production in pregnancy." (PMID 31533667, 2019). "Autoimmune thyroid diseases occur more often in those with systemic autoimmune diseases, and anti-TPO autoantibodies have been previously associated with ANA in healthy controls." (PMID 31354699, 2019). "Variants in the Tg gene or TPO gene have been linked to goiter, autoimmune thyroid diseases, and thyroid cancer." (PMID 28713435, 2017). "This means that only large-scale studies will unveil the association mood disorder-thyroid autoimmune disease as measured by the prevalence of TPO-Abs." (PMID 28108944, 2017). "Autoimmune thyroid disease is provoked by a loss of self-tolerance to the autoantigens thyroid peroxidase thyroglobulin, and thyroid stimulating hormone receptor, which leads to a destructive immune infiltration of the gland." (PMID 27064909, 2016). "Steroid responsive encephalopathy associated with autoimmune thyroiditis is an autoimmune encephalopathy associated with Hashimoto’s Disease and elevated serum levels of the related antibodies (anti-thyroid-peroxidase antibody or anti-thyroglobulin antibody)." (PMID 26209970, 2015). "Anti-TG and anti-TPO are associated with thyroid inflammation, and detection of these autoantibodies is a very specific means of diagnosing autoimmune thyroid disease." (PMID 24876839, 2014). "For example, autoimmune thyroiditis is common in T1D patients (15%–30%) and is associated with anti-thyroid peroxidase (TPO) and/or thyroglobulin autoantibodies." (PMID 23028856, 2012). "In autoimmune thyroid disease, systemic immune activation, antibody production (e.g., anti-TPO), and increased oxidative stress may elevate bands linked to proteins (immunoglobulins) and nucleic acids (cell death, turnover)." (PMID 40506941, 2025). "However, because of the possible negative effects of maternal anti-thyroid antibodies, we underline the importance of monitoring thyroid autoimmunity during pregnancy, including both anti-TG besides anti-TPO antibodies." (PMID 40128881, 2025). "Autoimmune disorders, such as antiphospholipid syndrome (APS) and thyroid autoimmunity (e.g., anti‐TPO antibodies), may cause uterine environment changes." (PMID 40325291, 2025). "However, several studies suggest that even subclinical thyroid autoimmunity, as indicated by elevated levels of TPO-Ab and TgAb, can increase the risk of pregnancy complications, even in women without overt thyroid disease." (PMID 41503315, 2025). "Notably, this phenotype is also associated with increased levels of thyroid autoimmunity markers, such as thyroid autoimmunity (TPO antibodies) and the inflammatory markers CRP and IL-6." (PMID 39749338, 2024). "Another theory posits that reduced TPO activity due to iron deficiency may contribute to an increase in thyroid autoimmunity." (PMID 39416653, 2024). "TPO antibodies can fix complement and may have a directly pathogenic role in autoimmune thyroid diseases." (PMID 37930957, 2023). "Anti-thyroid peroxidase antibody (TPO-Ab) is a main cause of auto-immune thyroiditis, and therefore euthyroid individuals positive for TPO-Ab might have latent damage to the thyroid gland." (PMID 37658108, 2023). "Anti-thyroid peroxidase antibody (TPO-Ab) is a known cause of autoimmune thyroiditis." (PMID 37658108, 2023). "For instance, serum AMH levels were lower in women with autoimmune thyroid disease (AITD), which may be due to the presence of thyroid peroxidase antibodies, indicating the association between autoimmune thyroiditis and decreased serum levels of AMH." (PMID 36595863, 2022). "Anti-thyroid peroxidase antibodies (TPO-Abs) are known to cause autoimmune thyroiditis." (PMID 35159980, 2022).
autoimmune thyroid disease (continued). "The HCP5 polymorphism rs3094228 investigated in this study has previously been associated with susceptibility to GD in a Polish cohort, and an association has been demonstrated between the C allele and thyroid peroxidase antibody levels in autoimmune thyroid disease." (PMID 32501499, 2020). "That is to say, what role TPO-abs, Tg-abs, and thyroid dysfunction play in the association between autoimmune thyroiditis and BD, particular RCBD remains unknown." (PMID 31791284, 2019). "Finally, although both TPO-abs and Tg-abs are biomarkers of autoimmune thyroiditis, it is still unclear which dominates the association between autoimmune thyroiditis and BD." (PMID 31791284, 2019). "This study and the previous one therefore underscore the widespread changes in immune-neuro-endocrine molecular networks that apparently precede the appearance of TPO-Abs, which opens avenues for developing assays for the detection of individuals at risk for thyroid autoimmunity." (PMID 27092550, 2016). "The presence of thyroid autoantibodies to thyroid peroxidase (TPO-Ab) and thyroglobulin (Tg-Ab) is common in women of reproductive age and is indicative of thyroid inflammation and an increased risk of developing autoimmune thyroid disease, such as Hashimoto’s thyroiditis." (PMID 25524327, 2016). "The hallmark of autoimmune thyroiditis is the presence of thyroid-specific autoantibodies in the serum, in particular anti-thyroglobulin antibodies (TG), anti-thyroperoxidase (TPO) antibodies and less frequently anti-TSH receptor antibodies, together with a variable degree of thyroid dysfunction." (PMID 15292926, 2004). "If future studies confirm a pathogenic role for anti-TPO antibodies, immunomodulatory interventions—such as B-cell depletion therapies—could be considered in select patients with progressive arteriopathy and serological evidence of thyroid autoimmunity." (PMID 40869987, 2025). "In another study, associations between vitiligo and anti-TPO (25.6%), anti-thyroglobulin (23.4%), antinuclear (16.8%), and anti-parietal cell (7.8%) antibodies were identified, noting that a total of 74 of the patients had autoimmune comorbidities (41.5%), mainly autoimmune thyroiditis." (PMID 36556267, 2022). "Compared to health control, the prevalence of antithyroid peroxidase antibodies (TPO-Abs) in bipolar offspring or co-twins of bipolar cases is also found to be higher, implying BD might share common genetic predisposition with autoimmune thyroiditis." (PMID 31791284, 2019). "The appearance of thyroid autoantibodies (in particular, antithyroid peroxidase; anti-TPO) in plasma and cerebrospinal fluid (CSF) is a necessary condition for the diagnosis of Hashimoto's encephalopathy (HE), a rare disease associated with autoimmune thyroiditis." (PMID 26798549, 2015). "Evidence of autoimmune thyroiditis, defined by elevated anti-TPO and/or anti-Tg, was observed in three patients (43%)." (PMID 41594321, 2026). "We also report the baseline prevalence of positive TPO and Tg antibodies across thyroid strata as surrogate markers of autoimmune thyroid disease." (PMID 41602965, 2026). "Her thyroid peroxidase and antinuclear antibodies positivity were incidental; PH is a distinct immunologic disorder mediated by IgE or T-cell responses and is unrelated to thyroid autoimmunity." (PMID 41472948, 2026). "This study represents the first investigation of the rs1126797 SNP located in exon 11 of the TPO gene in a Caucasian Polish population with autoimmune thyroiditis." (PMID 40650076, 2025). "By analyzing a cohort of 220 patients stratified by anti-TPO positivity, hsCRP levels, and thyroid function, we have provided detailed insights into the complex interplay between thyroid autoimmunity, systemic inflammation, and clinical symptoms." (PMID 39902025, 2025).